ZNF148 (zinc finger protein 148)
Description:
Involved in transcriptional regulation. Represses the transcription of a number of genes including gastrin, stromelysin and enolase. Binds to the G-rich box in the enhancer region of these genes.
Synonyms: BERF-1; ZBP-89; BFCOL1; HT-BETA; ZFP148; pHZ-52; GDACCF
Tractability: PROTAC: UniProt records ubiquitination sites on it; ubiquitination databases record sites on it; its protein half-life has been measured.
Gene: Protein-coding gene on chromosome 3 (125,225,669 to 125,375,842, reverse strand). Ensembl gene ENSG00000163848.
Subcellular location: Nucleus
Subcellular location (Human Protein Atlas): Nucleoplasm; Golgi apparatus
Gene Ontology:
Molecular function: DNA-binding transcription repressor activity, RNA polymerase II-specific; protein binding; RNA polymerase II cis-regulatory region sequence-specific DNA binding; sequence-specific DNA binding; DNA-binding transcription factor activity; transcription cis-regulatory region binding
Biological process: negative regulation of DNA-templated transcription; negative regulation of gene expression; negative regulation of transcription by RNA polymerase II; substantia nigra development; cellular defense response; regulation of transcription by RNA polymerase II
Cellular component: nucleoplasm; nucleus
Genetic constraint (gnomAD): Loss-of-function variants: 7 observed, 63.11 expected, observed/expected ratio (o/e) 0.11, 90% interval 0.062 to 0.21. The upper end of that interval is the gene's LOEUF score, 0.21, which puts it in group 1 of 6, group 1 being the genes least tolerant of losing a copy. Missense variants: 582 observed, 974.19 expected, observed/expected ratio (o/e) 0.6, 90% interval 0.56 to 0.64. Synonymous variants: 329 observed, 341.84 expected, observed/expected ratio (o/e) 0.96, 90% interval 0.88 to 1.05.
Homologues: Orthologues: chimpanzee ZNF148 (100% identical), macaque ZNF148 (99% identical), dog ZNF148 (99% identical), pig ZNF148 (99% identical), rabbit ZNF148 (99% identical), guinea pig ZNF148 (98% identical), mouse Zfp148 (98% identical), rat Zfp148 (97% identical), tropical clawed frog znf148 (61% identical), zebrafish znf148 (60% identical). Paralogues in human: ZNF281 (33% identical), MTF1 (13% identical), ZNF143 (12% identical), ZNF76 (12% identical), PATZ1 (11% identical), ZNF451 (11% identical), VEZF1 (10% identical), PRDM10 (10% identical), ZBTB16 (10% identical), PRDM1 (9% identical), MAZ (9% identical), ZNF384 (8% identical), and 24 more.
Diseases named in the same sentence as ZNF148 in open-access papers:
ZNF148 is named in the same sentence as 56 diseases in open-access papers, as found by Europe PMC text mining. Sharing a sentence is not in itself a finding about the gene and the disease. The quoted sentences say what the papers report.
breast carcinoma (9 papers, 2014 to 2024). "ZNF‐148 overexpression and downregulation vectors were transfected into breast cancer cells, and the associated malignant phenotypes were examined." (PMID 37909239, 2023). "Knockdown of ZNF148 increased the proposed pyroptosis‐associated biomarkers in breast cancer cells, indicating pyroptotic cell death." (PMID 37909239, 2023). "In parallel, both miR‐335 downregulation and SOD2 overexpression abrogated the antitumor effects of ZNF‐148 deficiency on proliferation and pyroptosis in breast cancer cells." (PMID 37909239, 2023). "In the present study, we identified a ZNF‐148/miR‐335/SOD2 axis in breast cancer cells, and we demonstrated that ZNF‐148 represses miR‐335 and then increases SOD2 expression, consequently decreasing pyroptosis in a ROS‐dependent manner." (PMID 37909239, 2023). "To date, studies on the role of ZNF‐148 in breast cancer have been limited, and the implications of its effects on breast cancer development are worthy of further investigation." (PMID 37909239, 2023). "This study sought to elucidate the potential molecular mechanism of ZNF‐148 on breast cancer pathology." (PMID 37909239, 2023). "Overexpression and downregulation of ZNF‐148 in breast cancer cells demonstrated that ZNF‐148 positively regulated SOD2." (PMID 37909239, 2023). "Specifically, the MTT assay results showed that knockdown of ZNF‐148 inhibited cell proliferation in breast cancer cells, while ZNF‐148 overexpression had the opposite effect." (PMID 37909239, 2023). "Taken together, we concluded that ZNF‐148 acts as an oncogene to facilitate breast cancer pathogenesis, and knockdown of ZNF‐148 triggers oxidative stress‐mediated pyroptotic cell death in breast cancer by downregulating SOD2 in a miR‐335‐dependent manner." (PMID 37909239, 2023). "Breast cancer tissues (n = 35) and their paired adjacent normal tissues (n = 35) were collected for further analysis, and qRT‐PCR analysis demonstrated that ZNF‐148 was upregulated in cancer tissues compared to normal tissues." (PMID 37909239, 2023). "The present study demonstrated that the expression of the proapoptotic protein, Bax, increased but that the expression of the antiapoptotic protein, Bcl‐2, decreased when ZNF‐148 was knocked down in breast cancer cells." (PMID 37909239, 2023). "Western blot analysis demonstrated that knockdown of ZNF‐148 increased the expression levels of pyroptosis‐associated biomarkers (NLRP3, ASC, IL‐1β, and IL‐18) in breast cancer cells, which was reversed by cotreating cells with NAC and ALA." (PMID 37909239, 2023). "It is possible that the effect of ZNF148 dosage in breast cancer is more pronounced in the context of MYC, stemness, and metastatic state of the cells." (PMID 36207293, 2022). "The genome-wide occupancy pattern of ZNF148 in breast cancer was consistent with our previous observation in hematopoietic cells." (PMID 36207293, 2022). "To determine the functional significance of ZNF148 in breast cancer, we used lentivirus to stably express ectopic ZNF148 cDNA into ER+ breast cancer (MCF7), TNBC (MDA-MB-231, BT549, and HCC1806), and normal-like breast (MCF10A) cell lines." (PMID 36207293, 2022). "To investigate if MYC transcriptionally regulates ZNF148 in breast cancer, we first examined the ChIP-seq data in the Encyclopedia of DNA Elements (ENCODE) database." (PMID 36207293, 2022). "Based on our finding, we posit that MYC negatively regulates ZNF148 to repress biological processes involving cellular differentiation and development, fostering cancer stem-cell-like features in breast cancer cells." (PMID 36207293, 2022). "SUZ12 and EZH2 occupancy, along with E-box motifs and MYC occupancy, and H3K27me3 marks at the regulatory region of the ZNF148 locus provide a possible mechanism for MYC-induced repression of ZNF148 in breast cancer." (PMID 36207293, 2022).
breast carcinoma (continued). "For example, ZBP89, also known as ZNF148, has been reported to have oncogenic functions in breast cancer, melanoma and gastric cancer, but repressing cell proliferation and inducing apoptosis in colorectal cancer." (PMID 35708873, 2022). "Collectively, these results support a direct transcriptional role for MYC in suppressing the expression of ZNF148 in breast cancer through chromatin occupancy." (PMID 36207293, 2022). "ZNF148 (also known as ZBP-89) regulates cell grwoth and apoptosis, having crucial roles in the developments of many cancers (e.g. gastric, colorectal, breast cancers)." (PMID 25151146, 2014). "We found that ZNF‐148 was upregulated in breast cancer tissues and cell lines." (PMID 37909239, 2023). "Knockdown of ZNF‐148 significantly increased the cell apoptosis ratio in breast cancer cells." (PMID 37909239, 2023). "Based on these findings, we hypothesized that miR‐335 may be the “bridge” to combine ZNF‐148 and SOD2 and that ZNF‐148 may be involved in breast cancer progression by targeting miR‐335/SOD2 signaling." (PMID 37909239, 2023). "Finally, we demonstrated that the miR‐335 mimic abrogated the promoting effects of ZNF‐148 overexpression in SOD2 in breast cancer cells, suggesting that miR‐335 is a link between ZNF‐148 and SOD2." (PMID 37909239, 2023). "This study may offer novel mechanistic insights into the excitatory signature of ZNF148 in the development of breast cancer." (PMID 37909239, 2023). "In addition, we investigated the role of the ZNF‐148/miR‐335/SOD2 pathway in regulating breast cancer pathogenesis and found that knockdown of ZNF‐148 suppressed cell viability by downregulating SOD2 by sequestering miR‐335." (PMID 37909239, 2023). "Further, we hypothesized that oxidative stress and pyroptosis may also be crucial for breast cancer pathogenesis mediated by ZNF‐148." (PMID 37909239, 2023). "Given that oxidative stress was closely associated with both cell apoptosis and pyroptosis and that ZNF‐148 regulated ROS production in breast cancer cells, we hypothesized that ZNF‐148 may regulate cell death in an oxidative stress‐dependent manner." (PMID 37909239, 2023). "ZNF148 expression was tested in breast cancer tissues and cells." (PMID 37909239, 2023). "Indeed, an inverse correlation between MYC and ZNF148 mRNA levels in breast cancer patients was observed." (PMID 36207293, 2022). "Future work to identify therapeutic agents that upregulate ZNF148 could be of clinical importance, not only in breast cancer, but in various cancers with aggressive cancer stem cell-like traits." (PMID 36207293, 2022). "Thus, ZNF148 functions as a tumor suppressor, promoting the differentiated state of breast cancer cells, and suppressing cell proliferation, metastasis, and biosynthetic programs associated with cancer stem cells." (PMID 36207293, 2022). "To identify downstream target gene(s) that enhance stem-like features in breast cancer, we ranked ZNF148 ChIP-enrichment scores, and the expression fold changes of genes within the enriched GO terms and identified Inhibitor of DNA binding 3 HLH protein (ID3) as a potential candidate." (PMID 36207293, 2022). "Of particular note, improved RFS associated with high ZNF148 expression was observed only in patients with lymph node-positive, but not in the lymph node-negative cases of breast cancer." (PMID 36207293, 2022). "Therefore, it is reasonable to speculate that there is a ZNF‐148/miR‐335 axis that regulates the cell pathogenesis of breast cancer." (PMID 37909239, 2023). "Our findings suggest that upregulating ZNF148 in breast cancer could also be beneficial." (PMID 36207293, 2022). "The present study identified a ZNF‐148/miR‐335/SOD2 feedback loop that regulates breast cancer development, thereby suggesting ideal targets for breast cancer treatment in the clinic." (PMID 37909239, 2023).
breast carcinoma (continued). "In addition, clonogenic assays, which measure stem-like cell growth in vitro, revealed increased colony formation in MDA-MB-231-ZNF148KO cells compared to the control, further validating our hypothesis that ZNF148 is a negative regulator of stemness in breast cancer." (PMID 36207293, 2022). "ZNF148 suppressed cell proliferation and migration and was transcriptionally repressed by MYC in breast cancer." (PMID 36207293, 2022). "The ZNF148 depletion increased the MYC transcript level in MCF10A-GFP cells, consistent with the inverse expression correlation found in breast cancer patients." (PMID 36207293, 2022). "Herein, we provide evidence for a direct transcriptional circuitry that functionally incorporates MYC, ZNF148, and ID1/3, regulating cancer stem cell traits in breast cancer." (PMID 36207293, 2022). "Despite ZNF148 being an established node of the MYC-network in ES cells, and the significance of MYC in driving cancer stem cells traits, the role of ZNF148 in breast cancer remains elusive." (PMID 36207293, 2022). "In this study, we uncover a novel role of ZNF148 in suppressing TNBC cell growth and metastasis and provide evidence for a direct regulatory circuitry between MYC, ZNF148, and ID1/3 that impacts stem cell traits in breast cancer." (PMID 36207293, 2022). "In summary, our study adds ZNF148 to a cadre of tumor suppressors that MYC actively represses, particularly in breast cancer." (PMID 36207293, 2022). "Upregulation of ZNF‐148 occupied miR‐335 in breast cancer cells, and the remaining miR‐335 was not sufficient to target the 3′‐UTR of SOD2 mRNA, resulting in SOD2 upregulation." (PMID 37909239, 2023). "The implication of zinc finger protein 148 (ZNF‐148) in pathophysiology of most human cancers has been reported; however, the biological functions of ZNF‐148 in breast cancer remain unclear." (PMID 37909239, 2023). "Our findings indicated that ZNF‐148 promotes breast cancer progression by triggering miR‐335/SOD2/ROS‐mediated pyroptotic cell death and aid the identification of potential therapeutic targets for breast cancer." (PMID 37909239, 2023). "In addition, knockdown of ZNF‐148 downregulated the expression of N‐cadherin and vimentin, which are involved in epithelial‐mesenchymal transition (EMT) in breast cancer cells." (PMID 37909239, 2023). "SOD2 has been demonstrated to be targeted by miR‐335,23 supporting our hypothesis that miR‐335 serves as a “bridge” to combine ZNF‐148 and SOD2 in breast cancer cells, and we demonstrated that a ZNF‐148/miR‐335/SOD2 pathway exists in breast cancer." (PMID 37909239, 2023). "Sodium butyrate, an HDAC inhibitor was shown to increase ZNF148 expression in colorectal cancer cells, however, it did not change the ZNF148 levels in breast cancer cells (data not shown)." (PMID 36207293, 2022). "Finally, we queried the METABRIC breast cancer patient data to examine the correlation between MYC, ZNF148, and ID1/3 expression levels." (PMID 36207293, 2022). "Furthermore, a direct proportional expression between MYC and ID1/3 was observed, further strengthening the existence of a MYC, ZNF148, and ID1/3 regulatory axis in controlling the stemness in breast cancer." (PMID 36207293, 2022). "Additionally, further cellular results validated that ZNF‐148 was enriched in breast cancer cell lines (T47D and MB468) but not in normal cells." (PMID 37909239, 2023). "Because both miR‐335 and SOD2 are involved in regulating pyroptosis, we next explored whether ZNF‐148 modulates this progression through the miR‐335/SOD2 axis by transfecting the ZNF‐148 silencing vector, miR‐335 inhibitor, and SOD2 overexpression vector into breast cancer cells." (PMID 37909239, 2023). "Confirming our previous observation in mouse ES cells, MYC occupancy was observed at the proximal promoter of ZNF148 in both MCF7 (ER positive, luminal subtype) and MCF10A (normal-like) breast cancer cells, and this region harbored several canonical and non-canonical E-box sequences." (PMID 36207293, 2022).
colorectal cancer (7 papers, 2016 to 2024). A primary or metastatic malignant neoplasm that affects the colon or rectum. "Two splicing isoforms of ZNF148 exerted mutual antagonistic effect to each other on the biological activities of colorectal cancer." (PMID 30640723, 2019).
melanoma (5 papers, 2017 to 2022). A malignant, usually aggressive tumor composed of atypical, neoplastic melanocytes. "To determine the effect of ZNF148 depletion on expression of TERT and CLPTM1L in pancreatic, lung, testicular, and melanoma cell lines (n=8 total), we used siRNA-mediated PTGS." (PMID 28447668, 2017). "Our results indicate that ZNF148 may regulate TERT expression in pancreatic, testicular, lung, and melanoma tumour cell lines via a regulatory element that is disrupted by the G allele at rs36115365." (PMID 28447668, 2017). "SPOP mutations have been found in TCGA prostate cancer (10.2%), but with ∼70% has altered either Tryptophan residue at 131 position or Phenylalanine residue at 133 position, while mutations of ZNF148 and EZH1 were commonly observed in melanoma as well with no hot mutation spot." (PMID 28580939, 2017).
colon cancer (4 papers, 2017 to 2025). "ZNF148 can inhibit the stemness transformation of liver cancer cells; however, ZNF148 knockdown can inhibit the growth of colon cancer." (PMID 41020579, 2025).
glioma (4 papers, 2023 to 2025). A benign or malignant brain and spinal cord tumor that arises from glial cells (astrocytes, oligodendrocytes, ependymal cells). "Notably, ZNF148 has been suggested as a potential regulator of TERT, which is associated with the prognosis of glioma patients." (PMID 41007824, 2025). "The transcription factor ZNF148 promotes the malignant transformation of dendritic cells after cross‐talk with glioma stem cells by upregulating PTX3, and reduce the expression of co‐stimulatory factors on the surface of DCs, inhibit their antigen presentation and activation of T cells." (PMID 37063077, 2023).
lung carcinoma (4 papers, 2017 to 2020). "Only the antibody against ZNF148 consistently resulted in loss of C allele-specific banding in pancreatic (PANC-1), as well as testis (NTERA-2) and lung cancer (A549) lines." (PMID 28447668, 2017).
adenoma (2 papers, 2016 to 2017). A neoplasm arising from the epithelium. "In familial adenomatous polyposis, expression of Znf148 increased from normal mucosa to adenomas to carcinomas, thus supporting the possibility that Znf148 promotes tumor initiation." (PMID 27487143, 2016).
Developmental delay (2 papers, 2016 to 2021). "The newly described ZNF148-associated syndrome is characterized by underdevelopment of the corpus callosum, mild to moderate developmental delay and ID, variable microcephaly or mild macrocephaly, short stature, feeding problems, facial dysmorphisms, and cardiac and renal malformations." (PMID 27964749, 2016). "Mutations in ZNF148 were associated with Global Developmental delay, Absent or hypoplastic Corpus Callosum and dysmorphic Facies (GDACCF)." (PMID 34976023, 2021).
microcephaly (2 papers, 2016 to 2020). A congenital or acquired developmental disorder in which the circumference of the head is smaller than normal for the person's age and sex. "Four patients harboring de novo truncating mutations in the ZNF148 gene shared core syndromic features including abnormal development of corpus callosum, microcephaly, ID, short stature, and facial dimorphisms." (PMID 32117005, 2020). "Four patients harboring de novo truncation mutations in the ZNF148 gene demonstrated overlapping clinical manifestations including ID, microcephaly, and mal-development of the corpus callosum." (PMID 32117005, 2020).
prostate carcinoma (2 papers, 2017 to 2022). A carcinoma that arises from epithelial cells of the prostate gland. "In TCGA database, the highest mutation frequency for SPOP was 7.63% (38/498) in prostate cancer, ZNF148 11.25% (9/80) in uveal melanoma 14.3%) and EZH1 11.25% (9/80) in uveal melanoma." (PMID 28580939, 2017).
astrocytoma (1 paper, 2023). "ZNF148 was also highly expressed in astrocytoma (Grade 1–2) and GBM samples according to the cancer genome atlas (TCGA) database." (PMID 37063077, 2023).
brain tumors (1 paper, 2023). "In PDXs, we observed top enriched terms for positively correlated genes for exercise‐induced circadian rhythm for brain tumors, cell–cell signaling, and ZNF148 transcription factor activity." (PMID 37533331, 2023).
esophageal squamous cell carcinoma (1 paper, 2025). Esophageal squamous cell carcinoma (ESCC) is a type of esophageal carcinoma (EC) that can affect any part of the esophagus, but is usually located in the upper or middle third. "hsa_circRNA_0101125 promotes esophageal squamous cell carcinoma progression by sponging miR‐143‐3p and upregulating ZNF148 expression." (PMID 41020579, 2025). "Inhibiting hsa_circRNA_0101125/miR‐143‐3p/ZNF148 might ameliorate esophageal squamous cell carcinoma progression." (PMID 41020579, 2025).
follicular thyroid carcinomas (1 paper, 2017). "We sequenced SPOPP94R and EZH1Q571R, and the last exon of ZNF148 in an additional set of 55 follicular thyroid carcinomas (FTC)." (PMID 28580939, 2017).